VCAM1 (vascular cell adhesion molecule 1)
Diseases named in the same sentence as VCAM1 in open-access papers (continued):
Sharing a sentence is not in itself a finding about the gene and the disease.
atherosclerosis (continued). "The expression of vascular cell adhesion protein 1 (VCAM1), a member of the immunoglobulin family mediating the adhesion of inflammatory cells to endothelia and suggested to play a role in atherosclerosis development, was also increased." (PMID 37686280, 2023). "Taken together, IL-32θA94V attenuated monocyte-endothelial adhesion by suppressing the expression of ICAM-1 and VCAM-1, which are key factors in atherosclerosis, via integrin-mediated signaling in HUVECs." (PMID 37228610, 2023). "Diosgenin prevents the intracellular adhesion molecule (ICAM-1), vascular cell adhesion molecule (VCAM-1), and protein expression involved in the development of atherosclerosis." (PMID 37520342, 2023). "We performed co-localization of immunofluorescence staining of CD31 and ICAM-1 or VCAM-1 in the aortic root sections of two stages of atherosclerosis." (PMID 36923537, 2023). "VCAM1 does an essential role in the occurrence of atherosclerosis through mediating the adhesion of immune cells such as monocytes and lymphocytes to vascular endothelium." (PMID 37168052, 2023). "P2Y2 deficiency lowers vascular cell adhesion molecule 1 (VCAM-1), which is known to induce leukocyte adhesion and atherosclerosis." (PMID 38270118, 2023). "MiR-126 inhibits VCAM-1 (vascular cell adhesion molecule 1), which in atherosclerosis interacts with inflammatory molecules to drive the formation of lesions." (PMID 36777351, 2023). "The VLA-4–binding Ile-Leu-Asp-Val (ILDV) moiety is an another notable peptide drug candidate that can competitively inhibit VCAM-1–mediated cell recruitment during atherosclerosis." (PMID 37595265, 2023). "ApoC-III shows proinflammatory properties related to its ability to increase binding to proteoglycans and monocytes to cultured endothelial cells through the induction of VCAM-1: for this reason, it has an important potential to facilitate atherosclerosis." (PMID 36689070, 2023). "VCAM-1 expression is enhanced in endothelial cells under proinflammatory conditions, as observed in the early stages of atherosclerosis." (PMID 36835296, 2023). "VCAM-1 encourages monocyte adherence and infiltration via endothelial cells into the subintimal layer, which contributes to the development of atherosclerosis." (PMID 37457745, 2023). "The recruitment of monocytes to the artery wall is an important step in the development of atherosclerosis and endothelial production of vascular cell adhesion molecule-1 (VCAM-1), which contributes to this process." (PMID 37727166, 2023). "The activated endothelial cells can increase the expression of soluble ICAM-1 and soluble VCAM-1, and these molecules can mediate leukocyte adhesion to the endothelium and activate atherosclerosis formation." (PMID 37144001, 2023). "Accumulated clinical and animal studies have shown that VCAM1 is activated in different cardiovascular events, such as atherosclerosis, stroke, and heart failure." (PMID 37841916, 2023). "Vascular cell adhesion molecule-1 (VCAM-1) is paramount to the initial development of atherosclerosis, and its activity has been suggested as an early indicator of at-risk vasculature for plaque formation; 82% of atherosclerotic lesions express VCAM-1." (PMID 37047696, 2023). "Studies in such VCAM-1–directed therapies so far remain scarce and are limited by the constraints of current experimental atherosclerosis models in accurately representing the complex pathophysiology of the disease." (PMID 37595265, 2023). "The favourable results of H6 and 7H aptly represent the therapeutic potential of VCAM-1–directed mAbs in ameliorating atherosclerosis." (PMID 37595265, 2023).
atherosclerosis (continued). "On the other hand, it promotes ROS release, increases ICAM-1 and VCAM-1 content, promotes monocyte migration and EC adhesion, and participates in the pathogenesis of atherosclerosis." (PMID 34981330, 2023). "This vast reservoir of potential peptide drug candidates, combined with the rapid advancement of biotechnologies and synthesis platforms, delineates an optimistic future for VCAM-1 peptide antagonists in atherosclerosis." (PMID 37595265, 2023). "In a functional model of the initial stages of atherosclerosis, EB prevents the adhesion of monocytes to EC by suppressing VCAM‐1 expression and the reduction of pro‐inflammatory cytokines." (PMID 37457144, 2023). "Meanwhile, genetic deficiencies of MCP-1, VCAM-1, and ICAM-1 have been believed to be related with decreased atherosclerosis." (PMID 36627567, 2023). "In high-fat diet-fed ApoE−/− mice, Romidepsin-enhanced STAT3 acetylation epigenetically modulates VCAM-1 expression to suppress atherosclerosis." (PMID 38031118, 2023). "The progression of atherosclerosis in mice and rabbits was evaluated using radiolabeled nanobodies with 64Cu for the screening of specific biomarkers such as (VCAM)-1, lectin-like oxidized low-density lipoprotein receptor-1 (LOX-1), and MMR." (PMID 37375810, 2023). "Adhesion molecules on the surface of circulating mononuclear cells mediate their attachment to vessel walls during atherosclerosis, including vascular cell adhesion molecule 1 (VCAM-1), platelet cell adhesion molecule 1 (PECAM-1), and ICAM-1." (PMID 37476573, 2023). "Both Fbln5 and Vcam1 were upregulated in genuine endothelial precursor cells of mice with advanced atherosclerosis administered with a Western diet, implying that it induced more leukocytes that migrated to sites of inflammation." (PMID 36910156, 2023). "Vascular cell adhesion molecule-1 (VCAM-1) has been well established as a critical contributor to atherosclerosis and consequently as an attractive therapeutic target for anti-atherosclerotic drug candidates." (PMID 37595265, 2023). "VCAM-1 is an endothelial adhesion molecule that participates in atherosclerosis by promoting monocyte adhesion, migration, and accumulation in the arterial intima." (PMID 37947623, 2023). "For example, nilotinib upregulates pro-atherogenic adhesion-proteins (ICAM-1 and VCAM-1), which induces atherosclerosis on the cell surface." (PMID 36814340, 2023). "For example, atherosclerosis can induce the expression of Vcam-1, Icam-1, Cxcl12, and Cx3cl1 in SMCs, which in turn facilitates binding to monocytes." (PMID 37686377, 2023). "It has been noted that HDAC1 can be involved in VCAM-1 expression and promotion of atherosclerosis through inhibition of STAT3 acetylation-dependent methylation of the GATA6 promoter." (PMID 37405052, 2023). "By limiting the expression of vascular cell adhesion molecule 1 (VCAM1), miR-126-3p reduces leukocyte adhesion to endothelial cells and prevents the further pathogenesis of atherosclerosis." (PMID 35892612, 2022). "Endothelial activation, an early process during atherosclerosis, is characterized by the expression of adhesion molecules such as the VCAM-1." (PMID 35892680, 2022). "VCAM-1 enables the adhesion of leukocytes to vascular endothelium, aggravating atherosclerosis and further facilitating inflammation." (PMID 35884827, 2022). "VCAM‐1, a member of the immunoglobulin superfamily, plays a key role in the development of atherosclerosis and rheumatoid arthritis." (PMID 35334492, 2022). "After the expression of LOX-1 in liver, Ox-LDL can be cleared by the hepatocytes, thereby reducing VCAM-1 expression in vascular endothelium and the migration of macrophages in plaques, and eventually alleviating the progression of atherosclerosis." (PMID 35236285, 2022).
atherosclerosis (continued). "And the endothelial cell dysfunction markers E-selection, ICAM-1, and VCAM-1 showed an increasing trend in the normal group, the diabetic group, and the diabetic with atherosclerosis group, which was consistent with the trend of QKi-7 among all groups." (PMID 35711530, 2022). "Out of these three, VCAM-1 is an important cell adhesion molecule that has a significant part in both the beginning stages of atherosclerosis as well as its later stages." (PMID 36408439, 2022). "CRP induces a significant increase in the expression of intercellular adhesion molecule-1 (ICAM-1) and vascular cell adhesion molecule-1 (VCAM-1), which accelerates the inflammatory response in atherosclerosis." (PMID 36418968, 2022). "This resulted in an increase in intercellular adhesion molecule 1 (ICAM-1) and vascular cell adhesion molecule 1 (VCAM-1), leading to mononuclear/endothelial cell adhesion and atherosclerosis." (PMID 36536469, 2022). "Although there are several ways to diagnose atherosclerosis, VCAM-1 represents a favorable target for molecular imaging-based non-invasive detection of atherosclerosis." (PMID 36408439, 2022). "The initial stage of atherosclerosis is due to endothelial dysfunction, which is associated with ICAM-1 and VCAM-1 overexpression." (PMID 36408439, 2022). "IL-17 mediates VCAM-1 expression in SMCs through multiple signaling pathways, thereby promoting atherosclerosis development." (PMID 36211578, 2022). "MMP8 plays a crucial role in the prognosis of sepsis patients based on the results of an in silico study, and MMP8 can promote the expression of VCAM-1 in patients with atherosclerosis." (PMID 35145983, 2022). "Cell adhesion molecules, such as VCAM-1, are commonly used as biomarkers of endothelial function and have been used as indicators of increased CVD and atherosclerosis risk and play an important role in plaque development." (PMID 36504827, 2022). "VCAM-1, an immunoglobulin superfamily glycoprotein, is expressed on the surface of the activated endothelium in the early stage of atherosclerosis." (PMID 36293254, 2022). "Oxidative stress and expression of the VCAM-1 on vascular endothelial cells are early features in the pathogenesis of atherosclerosis and other inflammatory diseases such as diabetes mellitus and chronic kidney disease." (PMID 36552558, 2022). "When examining atherosclerosis in a diabetic mouse model, H2S inhibited the formation of aortic root plaques, and downregulated the levels of vascular cell adhesion molecule 1 (VCAM1) and intercellular adhesion molecule 1 (ICAM1)." (PMID 35563208, 2022). "For instance, VCAM-1, a vial component of the leukocyte–endothelial adhesion molecule, is the most prevalent adhesion molecule in atherosclerosis (about 82%)." (PMID 36313319, 2022). "The NFκB upregulation leads to increasing its gene targets, including adhesion molecules, cytokines and chemokines (such as VCAM1, IL-6, TNFα and MCP-1), causing vascular inflammation and atherosclerosis." (PMID 35562979, 2022). "MBs can be associated with a nanobody targeting vascular cellular adhesion molecule 1 (VCAM-1) to target atherosclerosis plaques that induce VCAM-1 and image them." (PMID 35163604, 2022). "NF-kappa B promotes the expression of proinflammatory cytokines (such as IL-1, IL-6, and TNF-α) and various atherosclerosis-related genes (including VCAM-1, tissue factor, VEGF, and RAGE)." (PMID 35845584, 2022). "In the early stage of atherosclerosis, the expression of VCAM-1 and ICAM-1 is upregulated as the inflammatory response increases, and the increased expression of CAM promotes the accumulation of inflammatory leukocytes in the vascular endothelium." (PMID 35788200, 2022). "The EECP group had a significant reduction in atherosclerosis lesion, and a reduction in C-reactive protein, vascular cell adhesion molecule-1(VCAM-1), iNOS, mitogen-activated protein kinase phosphorylation (MAPK-p38), and activation of NFƙ-β." (PMID 36551807, 2022).
atherosclerosis (continued). "MAECs-expressed high levels of VCAM-1 are characteristic of cells at the site of atherosclerosis lesions." (PMID 35631669, 2022). "In turn, the resultant release of IL-1β leads to a dysfunctional endothelium and an increase in inflammatory mediators in the form of vascular cell adhesion protein 1 (VCAM-1), which contributes to atherosclerosis." (PMID 36362263, 2022). "VCAM-1, a protein expressed on the surface of activated endothelial cells, is considered an early manifestation of cholesterol-induced atherosclerosis." (PMID 35478972, 2022). "While most of the VCAM-1 targeting delivery systems were designed for the diagnosis and treatment of atherosclerosis, the applications have been broadened to other inflammatory diseases." (PMID 36105190, 2022). "Although VCAM-1 may be considered pharmacologically associated with stroke, it is closely involved in the progression of inflammatory and autoimmune disorders, including atherosclerosis, rheumatoid arthritis, multiple sclerosis, organ allografts, asthma, transplant rejection, and cancer." (PMID 35883879, 2022). "Atherosclerosis is preceded by the deposition of VCAM-1, an adhesion molecule that exists in two forms in humans and mice." (PMID 35759880, 2022). "During the early stages of atherosclerosis, an inflammatory environment can induce VCAM-1 expression, which promotes the activation and adhesion of leukocytes, resulting in dysfunctional vasculature." (PMID 35222039, 2022). "Most notably, Gal-3 and VCAM1, which have major participation in the pathogenesis of atherosclerosis, showed lower expression after a low-iron diet." (PMID 36555552, 2022). "Interacting with FOXO1, METTL14 acts directly on the promoter regions of ICAM-1 and VCAM-1 to upregulate their transcription, thereby mediating the inflammatory response of endothelial cells in atherosclerosis." (PMID 36482903, 2022). "Endothelial dysfunction is identified as an early indicator of atherosclerosis and is characterized by the high expression of VCAM-1 and ICAM-1." (PMID 35845572, 2022). "As we all know, MAPK/NF-κB cascade plays a critical role in the pathogenesis of atherosclerosis by modulating a series of adhesion molecules and inflammation-related genes including VCAM-1." (PMID 34858081, 2021). "For instance, mice with mutated VCAM-1 and ICAM-1 have decreased atherosclerosis compared to control mice." (PMID 34291056, 2021). "Both VCAM-1 and P-selectin are induced on the atherosclerotic plaques and are involved in the recruitment of monocytes into sites of atherosclerosis." (PMID 33839697, 2021). "As VCAM-1 usually indicates the infiltration of leukocytes such as monocyte, macrophage, or lymphocyte, it is thought to be a promising target to detect atherosclerosis and assess the efficacy of anti-atherogenic therapies." (PMID 34660748, 2021). "VCAM-1 expresses highly and has a major role in atherosclerosis development, which stresses the availability of VCAM-1 as an attractive target for atherosclerosis imaging." (PMID 34099630, 2021). "Considering the critical role of VCAM-1 in the development of atherosclerosis, considerable attention has been devoted to clarifying the regulation of VCAM-1 by cytokine in the endothelium." (PMID 34858081, 2021). "Overall, we herein found that HUVECs express high levels of G2A, which is thus a promising biomarker of atherosclerosis that can mediate the LPC-induced upregulation of ICAM-1/VCAM-1 via Gi-independent mechanisms." (PMID 34346841, 2021). "To explore a role of hyper-inflammability in senescent ECs in the progression of atherosclerosis, we analyzed the VCAM-1 expression in the endothelium of the plaque surface at an early stage." (PMID 34272458, 2021). "It was indicated that ER stress plays a role in the regulation of VCAM-1 transcription in endothelial cells during the process of atherosclerosis induced by postprandial lipemia." (PMID 33996937, 2021).
atherosclerosis (continued). "This imaging method for detection and quantification of VCAM-1 allows for early identification of inflammation in atherosclerosis." (PMID 35071257, 2021). "Activated platelets supported leukocyte adhesion to the arterial wall via stimulation of vascular cell adhesion molecule-1 (VCAM-1) and thereby promoted atherosclerosis." (PMID 33503867, 2021). "The combination of AGEs and receptor RAGE promotes the expression of a series of atherosclerosis-related genes such as vascular cell adhesion molecule-1, tissue factor, and monocyte chemoattractant protein-1." (PMID 34239586, 2021). "Microbubble contrast agents attached with antibodies to VCAM-1 (vascular cell adhesion molecule-1) or P-Selectin have demonstrated an increased affinity for inflamed endothelium in both advanced and early-stage atherosclerosis in animal studies." (PMID 34712527, 2021). "This has been especially the case in atherosclerosis with the use of AGI‐1067 therapy as an inhibitor of VCAM‐1 gene expression." (PMID 33559404, 2021). "The inhibition of IDO contributed to the remarkable aggravation of atherosclerosis in the aorta by up-regulating VCAM-1, CCL2, and rising CD68 macrophage accumulation in the lesions." (PMID 34199713, 2021). "Deficiency in CD36 has been shown to be reduce proinflammatory signaling, cell recruitment, Ccl2 and Vcam1 levels in models of ischemic stroke and atherosclerosis." (PMID 34496918, 2021). "Circulatory levels of proinflammatory molecules such as P‐selectin and VCAM‐1, which accelerate atherosclerosis progression, were lower in BALB than B6 mice." (PMID 34110700, 2021). "Next, we investigated if expression of most relevant genes (VCAM-1) involved in atherosclerosis was translated into respective change(s) in protein." (PMID 33925294, 2021). "VCAM-1 is the key link between microvascular endothelial activation during inflammation and arterial endothelial cell dysfunction in atherosclerosis." (PMID 35071362, 2021). "This enabled real-time assessment of VCAM-1 expression in atherosclerosis, which served as a proxy for activated cells in human plaques." (PMID 35071257, 2021). "As a result, sinomenine can be helpful to alleviate the endothelial inflammation in atherosclerosis by suppressing VCAM-1, IL-1, and ET-1." (PMID 34660748, 2021). "As expected, we observed that laminar shear stress induces cell shape change, up‐regulates vasoprotective genes (such as CPY1B1, THBD and NOS3) and, however, down‐regulates pro‐atherosclerosis genes (such as VCAM1, CD36, and ANGPT2)." (PMID 34085389, 2021). "Vascular cell adhesion molecule-1 (VCAM-1) peptide was also proposed as an inflammation-targeting peptide to identify the inflammatory activation of cells involved in atherosclerosis." (PMID 34067503, 2021). "In atherogenesis, ECs induce the expression of cell adhesion molecule, i.e., VCAM-1, to facilitate the adherence of monocytes to the endothelium as well as their infiltration into the vessel wall at the initiation of atherosclerosis." (PMID 34336268, 2021). "Adding to that, inhibition of basic fibroblast growth factor in the same vein graft atherosclerosis model resulted in decreased intraplaque angiogenesis and hemorrhage as well as reducing macrophage infiltration by reducing VCAM-1 expression." (PMID 33804952, 2021). "Atherosclerosis is a chronic progressive disease involving inflammatory events, such as the overexpression of adhesion molecules including the endothelial Vascular Cell Adhesion Molecule-1 (VCAM-1)." (PMID 34371717, 2021). "The use of functionalized USPIOs targeting VCAM-1, therefore, enables the visualization of these areas of arterial inflammation in atherosclerosis in animals and in humans." (PMID 33673124, 2021). "To verify the effect of the LPC-G2A-ICAM-1/VCAM-1 pathway on atherosclerosis, we next established the atherosclerotic rabbit models." (PMID 34346841, 2021).